CASP8 (caspase 8)
Diseases named in the same sentence as CASP8 in open-access papers (continued):
Sharing a sentence is not in itself a finding about the gene and the disease.
ovarian carcinoma (66 papers, 2006 to 2025). A malignant neoplasm originating from the surface ovarian epithelium. "According to the downregulation of caspase-8, ovarian cancer is linked to high aggressiveness, chronic inflammation, immunoediting, and immune resistance." (PMID 40674382, 2025). "To determine the significance of CASP8 expression in the prognosis of ovarian cancer patients, we analyzed the association of CASP8 expression with clinical variables from TCGA for ovarian serous adenocarcinoma (OV-TCGA)." (PMID 38201534, 2023). "In breast and ovarian cancers, the downregulation of caspase-8 seems to be associated with bad prognosis and therapy resistance." (PMID 33026575, 2021). "The downregulation of caspase-8 in ovarian cancer seems to be linked to high aggressiveness with chronic inflammation, immunoediting, and immune resistance." (PMID 33026575, 2021). "Ovarian cancer subtypes with increased expression of caspase-8 are associated with higher infiltration of T cells, better response to chemotherapy, and longer overall survival (OS)." (PMID 33026575, 2021). "We also showed that ovarian cancers depleted of Caspase 8 can be susceptible to cell death by caspase-independent necroptosis." (PMID 34088893, 2021). "We found that high expression of p62 and Caspase 8 is associated with favourable prognosis and progression of ovarian cancer." (PMID 30941888, 2019). "To evaluate the effect of high expression of p62 and Caspase 8 in ovarian cancer, we established tumour xenografts by inoculating A2780 ovarian cancer cells in immune‐deficient BALB/C nude mice." (PMID 30941888, 2019). "In this study, our data indicated that high expression of p62 and Caspase 8 were associated with longer survival time and less relapse in ovarian cancer." (PMID 30941888, 2019). "Moreover, they found that impaired caspase-8 expression in ovarian cancer occurs as a result of mutations, deletions, or complete lack of expression of the enzyme." (PMID 33919909, 2021). "Berberine alone or combined with cisplatin may induce ovarian cancer cells to arrest at the G0/G1 phase and enhance the activity of cell death-associated proteins, including caspase-8 and caspase-3, thereby promoting apoptosis and necrosis." (PMID 32934709, 2020). "has reported that an apoptosis-enhancing drug, birinapant, aimed at eliminating the CSC subpopulation in ovarian cancer, re-sensitized ovarian cancer cells to carboplatin via cleavage of caspase 8 and restoration of apoptosis caused by degradation of baculoviral IAP repeat containing 3 (cIAP)." (PMID 31193124, 2019). "Moreover, we found that deletion of EGFL6 could decrease the expression of Bcl-2 and increase the expression of Bax and Caspase-8, which could activate the Caspase-3 signal pathway and cause apoptosis of ovarian cancer cells." (PMID 32983976, 2020). "Furthermore we provide evidence that p62 regulates autophagic flux through its autophagy‐related domains and suppression of autophagic flux promotes Caspase 8 recruitment and activation caused by p62 accumulation, which increases the sensitivity of ovarian cancer cells to cisplatin." (PMID 30941888, 2019). "This study’s findings suggest that Axitinib and SDC interact with the targeted and selected protein receptor (Caspase-8 protein) on breast and ovarian cancer through a variety of hydrogen, conventional, covalent, and pi alkyl bonding interactions." (PMID 40674382, 2025). "A recent study demonstrated that PARP inhibitors induce pyroptosis in ovarian cancer via a TNF–caspase-8–GSDMD/E axis, generating immunogenic cell death that remodels the tumor immune microenvironment and expands T cells specific for tumor-derived neoantigens." (PMID 41291696, 2025). "In this study, we have demonstrated that low Caspase-8 expression correlates with poor prognosis in ovarian cancer patients." (PMID 38201534, 2023).
ovarian carcinoma (continued). "Our work here has demonstrated that the low expression of Caspase-8 in ovarian cancer patients has a significantly poorer prognosis compared to Caspase-8-expressing patients." (PMID 38201534, 2023). "Intriguingly, in ovarian cancer patients, low CASP8 expression was correlated with advanced clinical stages, although no corresponding correlation with higher tumor grades was observed." (PMID 38201534, 2023). "Here, we discovered that the SMM extract induced the activation of caspase-8-dependent apoptosis in human ovarian cancer cells." (PMID 37507925, 2023). "Rogalska and Marczak observed in OV-9 (ovarian cancer cells) that EpoB triggers TRAIL/caspase 8-dependent apoptosis, an apoptosis pathway that simultaneously causes mitochondrial alteration." (PMID 37047035, 2023). "A preclinical study showed that the small molecule SMAC mimic LBW242 strongly synergized with tumor necrosis factor-related apoptosis inducing ligand (TRAIL) or anticancer drugs to induce apoptosis of ovarian cancer cells by activating caspase-8." (PMID 37270486, 2023). "In this study, we have determined that low Caspase-8 expression in ovarian cancer patients leads to poor prognosis." (PMID 38201534, 2023). "In summary, this data establishes the prognostic significance of CASP8 expression for ovarian cancer patients." (PMID 38201534, 2023). "Considering the role of Caspase-8 as an inhibitor of transcriptional elongation in cancer cells we explored previously, we initiated a molecular investigation in ovarian cancer cells." (PMID 38201534, 2023). "In ovarian cancer, caspase-8 can modulate B and T lymphocyte activation, as well as macrophage differentiation and polarization." (PMID 35928267, 2022). "A clinical study demonstrated that ovarian cancer patients who had tumors with low levels of expression of caspase-8 had reduced survival rates, whereas patients with higher levels of caspase-8 had longer survival rates." (PMID 36551731, 2022). "Our previous study showed that p62 is a bridge for Caspase 8 recruitment and activation on the autophagosome membrane in ovarian cancer cells." (PMID 35328718, 2022). "Gynecological cancers such as breast and ovarian cancers seem to be more aggressive when caspase-8 is downregulated." (PMID 33026575, 2021). "The aim of this study was to evaluate serum levels of caspase-3, caspase-8, and caspase-9 in women with ovarian cancer." (PMID 33919909, 2021). "The same group showed decreased caspase-8 activation and platin resistance in p62-mutant ovarian cancer cells." (PMID 33026575, 2021). "Ovarian cancer often has dysregulated caspase-8 expression, leading to imbalance between its apoptotic and non-apoptotic functions within the tumor and the surrounding milieu." (PMID 33026575, 2021). "The aim of this study was to analyze the soluble markers monitoring the apoptosis process by assessing the levels of caspase-3, caspase-8, and caspase-9 in the serum of women with ovarian cancer." (PMID 33919909, 2021). "A xenograft ovarian cancer mouse model demonstrated that the autophagy inhibitor, chloroquine, promoted the accumulation of p62 and increased caspase-8 levels, which improved the response to cisplatin and enhanced apoptosis." (PMID 33026575, 2021). "Serum levels of caspase-3, caspase-8, caspase-9, and CA 125 antigen were determined in healthy women belonging to the control group and women with ovarian cancer." (PMID 33919909, 2021). "Low Caspase 8 expression levels in ovarian cancers correlate with resistance to apoptotic chemotherapy, and a subpopulation of patients with low Caspase 8 levels exhibit poorer overall survival after standard-of-care treatment." (PMID 34088893, 2021). "The comparison of caspase-8 and CA 125 antigen concentrations in serum of women with ovarian cancer and healthy women was also made." (PMID 33919909, 2021).
ovarian carcinoma (continued). "We investigated the in vitro effect of Smac-mimetic added to carboplatin and paclitaxel treatment of ovarian cancer cells expressing wild type and low Caspase 8 levels, which resulted in a 2–4-fold enhancement of cell death." (PMID 34088893, 2021). "More recently, we have shown that Caspase 8 plays a dual role in ovarian cancer, regulating apoptosis and necroptosis downstream of TNFαR15." (PMID 34088893, 2021). "Further studies are needed to clarify the role of cFLIP in p62-mediated caspase 8 activation in ovarian cancer with cisplatin treatment." (PMID 32322174, 2020). "Overall, we found that PCBP1, p62, and Caspase-8 expression levels were correlated with each other in ovarian cancers." (PMID 32922440, 2020). "We previously found that deleting the p62 UBA domain, which is responsible for ubiquitin binding and self-oligomerization, inhibited cisplatin-induced caspase 8 activation, leading to chemoresistance in ovarian cancer cells." (PMID 32322174, 2020). "In our previous study, (−)-9′-O-(α-l-rhamnopyranosyl)lyoniresinol, a lignan with rhamnose, induced apoptosis in A2780 human ovarian carcinoma cells through the induction of the extrinsic apoptotic signaling pathway via the activation of caspase-8." (PMID 32276430, 2020). "Although we demonstrated the role of high expression of p62 and Caspase 8 in ovarian cancer, there are still many issues to be further investigated." (PMID 30941888, 2019). "Together these findings suggested that p62 mediates Caspase 8 activation in response to cisplatin in an ubiquitin‐binding and autophagic membrane‐dependent manner in ovarian cancer cells." (PMID 30941888, 2019). "We found that p62 with Caspase 8 high expression is correlated with longer survival time compared with cases of low Caspase 8 expression in ovarian cancer." (PMID 30941888, 2019). "APG-1387 induced RIP1- and TNFα-dependent apoptotic cell death in ovarian cancer through downregulation of IAPs proteins and induction of caspase-8/FADD/RIP1 complex, which drives caspase-8 activation." (PMID 29530056, 2018). "Actin depolymerization accelerated caspase-8 activation, while LPA inhibited the association and activation of caspase-8 at the DISC in epithelial ovarian cancer OVCAR3 cells." (PMID 26366416, 2015). "Cisplatin enhances rhTRAIL-induced apoptosis in cisplatin-resistant ovarian cancer cells, and induction of caspase 8 protein expression is the key factor of rhTRAIL sensitisation." (PMID 21487429, 2011). "In the present study, we show that the cellular caspase 8 protein level is an important determinant of sensitivity to rhTRAIL-induced apoptosis in an isogenic ovarian cancer cell line model of acquired cisplatin resistance." (PMID 21487429, 2011). "Fenretinide is also reported to activate caspase-8 and caspase-9 in glioblastoma, meningioma and ovarian carcinoma." (PMID 20877355, 2010). "Similar caspase-8 activation has been described in 4-HPR-induced cell lines such as ovarian cancer cell lines or Fas-defective hepatoma cells." (PMID 19331667, 2009). "Therefore, we then evaluated caspase-8 expression, known to play a pivotal role in the extrinsic pathway, and our results revealed a significant increase in the cleavage of caspase-8 in ovarian cancer cells treated with UDAE." (PMID 39456397, 2024). "In summary, these findings lead us to conclude that the BRD4 expression is elevated in HGSOC cell lines lacking the Caspase-8 expression, and the overexpression of BRD4 significantly shortens OS in ovarian cancer patients, mainly when the Caspase-8 expression is low." (PMID 38201534, 2023).
ovarian carcinoma (continued). "Similarly, matrine not only reduces the expression level of Bcl-2 and increases the expression of caspase-8, but also inhibits the viability, and migration and induces apoptosis of ovarian cancer cells by up-regulating the p38MAPK and JNK pathways." (PMID 36686745, 2022). "The experimental results suggested that SH-6 could pass P38, mitogen-activated protein kinase (MARK), and Caspase-8-dependent BID decomposition pathways to induce apoptosis of ovarian cancer cell A2780." (PMID 35529935, 2022). "Caspase 8 is involved in this complex mechanism mediating pro-survival NFκB signaling or triggering extrinsic apoptosis downstream of short-term stimulation with TNFα in ovarian cancer cells." (PMID 34088893, 2021). "The presence or absence of caspase-8 determines the invasiveness and migration of tumor cells, and decreased expression of this enzyme in women with ovarian cancer is associated with increased aggressiveness and poor prognosis due to resistance to therapy." (PMID 33919909, 2021). "Further analysis included evaluation of caspase-8 serum levels in women with ovarian cancer." (PMID 33919909, 2021). "It is still unclear how exactly caspase-8 is involved in chemoresistance in ovarian cancer." (PMID 33026575, 2021). "In ovarian cancer, the genetic modifications of caspase-8 are estimated at 2.4%." (PMID 33026575, 2021). "Therefore, the aim of the present study was to evaluate serum levels of caspase-3, caspase-8, and caspase-9 in women with ovarian cancer." (PMID 33919909, 2021). "Importantly, in this model, the survival of the mice bearing the more aggressive Caspase 8-low ovarian cancer cells reached that of the mice with the Caspase 8-high tumors." (PMID 34088893, 2021). "Moreover, two research groups had independently described the essential role of caspase-8 in the first-line therapy of ovarian cancer." (PMID 33026575, 2021). "In vitro and in vivo, we found ovarian cancer cell death to be similarly pronounced in both Caspase 8 high-expressing and low-expressing ovarian cancers after combined treatment, suggesting that survival benefits may be possible with this therapeutic approach." (PMID 34088893, 2021). "Ovarian cancer cells with low caspase-8 expression are resistant to apoptosis, but when the IKKβ inhibitor IV, which suppresses the NFκB pathway, is combined with the SMAC mimetic Birinapat, which inhibits cIAP, cancer cells are forced toward necroptosis in a RIPK1-dependent manner." (PMID 33026575, 2021). "In addition, quercetin upregulated the expression of miR-145, and then activated caspase-8, caspase-9 and caspase-3, which induced the apoptosis of ovarian cancer cells." (PMID 32934709, 2020). "Together, these results indicated that p62 and Caspase 8 may be prognostic factors for survival in ovarian cancer." (PMID 30941888, 2019). "Furthermore, p62 functional domain UBA and LIR mutants regulated autophagic flux and attenuated Caspase 8 activation, which indicates that autophagic degradation is involved in p62‐mediated activation of Caspase 8 in ovarian cancer cells." (PMID 30941888, 2019). "p62/Caspase 8 may become promising prognostic biomarkers and onctargets for ovarian cancer treatment." (PMID 30941888, 2019). "p62 and Caspase 8 may become novel prognostic biomarkers and oncotargets for ovarian cancer treatment." (PMID 30941888, 2019). "As we aimed to determine whether the recruitment of Caspase 8 could affect the role of p62 in ovarian cancer patients, we focused on ovarian cancer samples subtypes with high p62 expression/ high Caspase 8 expression and high p62/ low Caspase 8 expression." (PMID 30941888, 2019). "Our results demonstrate that p62 and Caspase 8 may serve as potential prognostic biomarkers and oncotargets for individualized treatment of ovarian cancer patients." (PMID 30941888, 2019). "In addition, (−)-asarinin increased the activation of caspase-3, caspase-8, and caspase-9 in ovarian cancer cells." (PMID 30044423, 2018).
ovarian carcinoma (continued). "Consequently, these data propose that the Caspase-8 expression could serve as a valuable factor for patient stratification and predicting the effectiveness of the recommended hormonal therapy for ovarian cancer patients." (PMID 38201534, 2023). "In ovarian cancer cell line A2780 treated with this treatment, the percentage of apoptotic cells and nuclear condensation was increased in a concentration-dependent manner, and the expressions of caspase 8, caspase 3, caspase 9, and Bax were increased, while the expression of Bcl-2 was decreased." (PMID 36686745, 2022). "Furthermore, it was concluded that the assessment of serum caspase-8 and CA 125 marker levels may be useful in the diagnosis of ovarian cancer, but this requires further research." (PMID 33919909, 2021). "In addition, p62 and caspase 8 are responsible for the progression of ovarian cancer." (PMID 33924293, 2021). "In the current study, we show that ovarian cancers expressing low levels of Caspase 8 may be resistant to standard apoptotic-inducing chemotherapy treatments, because they exhibit poorer prognosis than ovarian cancers expressing high Caspase 8 levels." (PMID 34088893, 2021). "The results suggest that both NFκB-dependent and NFκB-independent ovarian cancer cells can be targeted for additional cell death by chemotherapy and birinapant combined treatment, though the magnitude of effect may differ based on Caspase 8 expression." (PMID 34088893, 2021). "In ovarian cancer, CRABP2 promotes tumorigenesis and olaparib resistance through downregulation of caspase-8 while decreasing reactive oxygen species production." (PMID 40657374, 2025). "According to the results of tests conducted on A2780/CP70 ovarian cancer cells, KEM significantly increased the cleavage of PARP-1 and the activity of caspase-3/7, as well as the activity of caspase-8 and -9 common to both pathways." (PMID 38674891, 2024). "We identified a series of necroptosis‐related genes involved in the pathogenesis of ovarian cancer, including STAT1, CASP8, and IFNB1, and provided a preliminary analysis of their interactions." (PMID 37681751, 2023). "Using representative ovarian cancer cell lines, we show that the SMAC-mimetic birinapant combined with chemotherapy increased cell death in cells with low Caspase 8, representing the poor prognostic subgroup." (PMID 34088893, 2021). "Ultrasound-targeted microbubble destruction accelerated the apoptosis of ovarian cancer OVCA-433 cells by upregulating the expression of caspase-3 and caspase-8." (PMID 34949962, 2021). "Given the variety of roles of caspase-8 in the TME, we should focus on this protein in the development of new therapeutic strategies against the TME of ovarian cancer." (PMID 33026575, 2021). "As shown in previous studies using human nasopharyngeal and ovarian carcinoma cells, our results demonstrate that LCA activated caspase-3 as well as caspase-8 and -9, and induced the cleavage of PARP." (PMID 31387245, 2019). "We first investigated the expression of RIPK1, RIPK3, caspase-8 and MLKL in a panel of ovarian cancer cell lines as well as HeLa cells." (PMID 29238045, 2017). "Protein expression levels of cleaved caspase-3, caspase-8, caspase-9, and PARP in the A2780 ovarian cancer cells markedly increased, whereas the expression of BID decreased after 20(S)-Rg3 treatment." (PMID 27051448, 2016). "The activity of caspase 3 and 9 had an obvious increase, but the activity of caspase 8 had little changes between control and MIL-treatment cells in both ovarian cancer cells." (PMID 27447570, 2016).